CGAS (cyclic GMP-AMP synthase)
Diseases named in the same sentence as CGAS in open-access papers (continued):
Sharing a sentence is not in itself a finding about the gene and the disease.
infection (continued). "Our present results reiterate the necessity of cGAS and IFI16 to drive interferon responses in the human macrophage-like cell line THP-1 during infection with HIV, HSV-1 and CMV or by stimulation with synthetic DNA." (PMID 28186168, 2017). "At 24 hrs post-infection, increased levels of DENV RNA in cGAS-silenced A549 cells were detected compared to cells transfected with scrambled siRNA control." (PMID 28620207, 2017). "Surprisingly, infection with viral dsDNA revealed an IFN inhibitory role and therefore pro-viral function of OASL through the inhibition of the cGAS cytosolic DNA sensing mechanism." (PMID 28580319, 2017). "c-di-GMP enters mammalian cells through infection with bacteria, while 2′3′-cGAMP is endogenously produced by cGMP-AMP synthase (cGAS) in response to invasion with foreign DNA, which directly activates cGAS." (PMID 26013485, 2016). "Notably, TLR signaling genes interferon regulatory factor 1 (IRF1) and MyD88 are significantly induced by MVA infection in DSK cells, probably to counterbalance the reduced IFN-I response of the cytosolic DNA-sensing cGAS/STING/IRF3 axis." (PMID 40981440, 2025). "Since its discovery, cGAS has been thought to recognize cytoplasmic mislocalized double-stranded DNA (dsDNA) in a sequence-independent manner, but its relevance in HIV-1 natural human infection is still uncertain and variable according to cell type." (PMID 41041557, 2025). "Since cGAS is a cytosolic DNA sensor, we examined whether PCV2 Rep also localizes to the cytoplasm during infection." (PMID 40523029, 2025). "In infectious diseases, elevated expression or activity of cGAS-STING pathway molecules may indicate pathogen invasion (e.g., viruses, bacteria), aiding diagnosis of infection type and severity." (PMID 41007720, 2025). "For instance, a novel X-ray-inactivated PA whole-cell vaccine induces the release of bacterial nucleic acids, activating the cGAS-STING signaling in dendritic cells and subsequently inducing pathogen-specific T-cell responses, thereby enhancing host resistance to infection." (PMID 40697819, 2025). "We studied whether these two viral proteins enable cGAS and STING degradation, thereby preventing DNA sensing during the infection." (PMID 39836220, 2025). "Indeed, cytokines have been shown in literature to modulate synaptic connectivity and neuronal function.This finding is compatible with the activation of the cGAS-STING pathway and is consistent with the response of the pathway to infection." (PMID 41139159, 2025). "During pathogen infection, cyclic GMP-AMP synthase (cGAS) can directly sense pathogen-derived DNA, catalyzing the synthesis of cGAMP from ATP and GTP, which subsequently activates the downstream host cell STING/tank-binding kinase 1/interferon regulatory factor 3/IFN-β signaling pathway." (PMID 41396345, 2025). "The cGAS-STING pathway, which evolved as a bacterial antiphage mechanism to detect exogenous and endogenous DNA, plays a pivotal role in inflammatory responses during infections, cellular stress, and tissue injury." (PMID 40351606, 2025). "After infection of macrophages by L. monocytogenes, bacterial RNA is recognized by the cytosolic sensors RIG-I and MDA5, while bacterial DNA activates the DNA sensors IFI16 and cGAS to induce the production of type I IFNs." (PMID 40137714, 2025). "Furthermore, infection by RNA viruses, such as SFTSV and dengue virus, can also be sensed by the cytoplasmic DNA sensor cGAS, through inducing mitochondrial DNA (mtDNA) leakage into the cytoplasm for cGAS recognition." (PMID 40689679, 2025). "The TLR9 and cGAS DNA pathways are two major signaling pathways detecting self and non-self DNA to mount immune responses against infection and tumorigenesis." (PMID 40337520, 2025). "In BHK21 cells, although the expression of some ISGs is upregulated upon MVA infection, the cGAS/STING axis does not serve as the primary mediator of the antiviral response, suggesting alternative sensing mechanisms." (PMID 40981440, 2025).
infection (continued). "However, during natural infection, HPV is contained in a vesicular trafficking pathway that shields it from cGAS-STING detection." (PMID 40430784, 2025). "As with all sensing events, activation is dose-dependent and we propose that WT HIV-1(M) infection does not typically activate cGAS unless high infection doses are used." (PMID 39804283, 2025). "The cyclic-GMP-AMP synthase (cGAS) - stimulator -STING (stimulator of interferon genes) signaling pathway is crucial for initiating IFN gene production in response to tissue injury, cellular stress, and infection." (PMID 40026316, 2025). "Concurrent with our results, the Biolatti Laboratory, which discovered pp65 as a restriction factor for cGAS, also observed no degradation of cGAS, and our previous work identified that infection with WT HCMV does not degrade STING." (PMID 40243337, 2025). "Moreover, PCV2d infection significantly decreased the production of 2’,3’-cGAMP and IFN-α secretion, further confirming the suppression of the cGAS-STING pathway." (PMID 40523029, 2025). "Although only astrocytes permit effective infection, both iPSC astrocytes and HMC3 microglia showed signs of senescence, recruitment of foci compatible with DNA damage accumulation and activation of the cGAS-STING pathway." (PMID 41139159, 2025). "Infection with SARS-CoV-2 leads to mitochondrial dysfunction and nuclear envelope rupture, releasing the nuclear and mtDNA into the cytoplasm, which activates the cGAS-STING pathway, promoting antiviral responses and inhibiting viral replication." (PMID 40697819, 2025). "Manganese (Mn2+), a robust stimulator of type I interferon, activates the cGAS-STING pathway even without infection, showcasing its potential in immunotherapy." (PMID 38817608, 2024). "Also the infection with IAV stimulates the release of mtDNA and subsequently the activation of the cGAS-STING axis." (PMID 39543713, 2024). "Inhibitors for cGAS (RU.521), as well as TBK-1 (BX795), were used prior to infection." (PMID 39459875, 2024). "We observed that the wild-type and cGAS−/− mice were both resistant to the infection of SFTSV, and no mouse died of SFTSV infection in both groups." (PMID 38712963, 2024). "Ongoing clinical trials of cGAS-STING signaling pathway primarily focused on antitumor immunity, whereas, due to growing evidence tapping into the potential of anti-viral immunity, making it a new strategy for the treatment of infections." (PMID 38693578, 2024). "In this pathway, it was demonstrated that ISGylation is involved in regulating the activity of the DNA sensor cGAS, which enhances cGAS’ oligomerization and activity after Herpes simplex virus 1 (HSV-1), also known as Human alphaherpesvirus 1 (HHV-1), infection." (PMID 38675828, 2024). "Therefore, the cGAS/STING/NLPR3 axis can be targeted in sterile inflammatory conditions such as MDS, DN, and infections." (PMID 38339107, 2024). "dsDNA from a variety of pathogenic microorganisms such as mycobacterium tuberculosis, adenovirus and plasmodium falciparum is recognized by cGAS, which then promotes the expression of type I IFN and proinflammatory cytokines to enhance the anti-infection immunity." (PMID 38515746, 2024). "The effect on FMDV infection of treatment with inhibitors of the cGAS/STING signaling has also been studied and our results support the relevance of this DNA sensing pathway restricting infection by FMDV which in turn has evolved a reinforced counteracting strategy." (PMID 38509419, 2024). "The cGAS-STING [(cGAMP) synthase (cGAS)-interferon gene-stimulating factor (STING)] signaling pathway is a mediator of the inflammatory response under stress, infection, and tissue injury." (PMID 38515787, 2024). "Western blot revealed no significant increase in the cGAS levels upon HP-PsV infection nor did it show any clear differences between CTRLko and LMNB1ko cells." (PMID 38485766, 2024).
infection (continued). "Therefore, the cGAS/STING system is critical for infectious diseases and their progression to life-threatening infections." (PMID 38339107, 2024). "The cyclic GMP-AMP synthase-stimulator of interferon genes (cGAS-STING) signaling pathway plays an important novel role in the immune system and has been confirmed to be a key mediator of inflammation during infection, cellular stress, and tissue damage." (PMID 39113033, 2024). "Intriguingly, while UL138 expression reduced IFNB1 and CXCL10 accumulation downstream of cGAS-STING-TBK1, it has also been reported to enhance the expression of some interferon stimulated genes (ISGs) at late times during productive infection, presumably by promoting the activation of STAT1." (PMID 38932169, 2024). "Significant differences in the abundance of mtDNA fragments bound to cGAS were observed between mock THP-1 cells and SFTSV-infected THP-1 cells, which suggested that mtDNA was enriched and bound to cGAS under SFTSV infection." (PMID 38712963, 2024). "DNA from L. monocytogenes is sorted into EVs in infected cells through a STING-TBK1-MVB12b (multivesicular body protein) pathway and delivered to bystander cells to stimulate cGAS-STING pathway, which facilitates the spread of infection signs across tissues prior to the actual infection process." (PMID 36825026, 2023). "The cyclic GMP-AMP synthase (cGAS)-stimulator of interferon genes (STING) pathway is a cytosolic double-stranded DNA sensor of the innate immune system, which is important in the response to pathogen infection and inflammation." (PMID 37355491, 2023). "The cGAS-STING pathway has been reported to strongly evoke IFN responses and effectively inhibit infection by several other RNA viruses, such as chikungunya virus (CHIKV), encephalomyocarditis virus (EMCV), hepatitis C virus (HCV), murine norovirus (MNV), Nipah virus (NiV), and Zika virus (ZIKV)." (PMID 37744905, 2023). "Thus, MDA5 and cGAS mainly contribute to the production of types I/III IFNs and proinflammatory cytokines in epithelial cells in the early phase of infection." (PMID 36703213, 2023). "Among them, cGAS-STING signaling is the most widely studied immune pathway participating in innate immunity against Plasmodium, Toxoplasma gondii (T. gondii), Trypanosoma cruzi (T. cruzi), and Schistosoma mansoni (S. mansoni) infection." (PMID 36825026, 2023). "Mn2+ directly activates cGAS without DNA and triggers a distinct catalytic synthesis of 2’3’-cGAMP,so Mn2+ can induce cells to produce type I IFNs without any infection." (PMID 37153576, 2023). "Since the kynurenine pathway is downstream of the cGAS-STING viral/pathogen sensing pathway, this observation could contribute to explaining why disease severity worsens in LN patients upon infection." (PMID 37760001, 2023). "As the cGAS-STING axis plays a crucial role in host antiviral defense, many viruses have evolved various mechanisms to antagonize this signaling pathway for efficient infection and replication." (PMID 37228597, 2023). "Although studies have shown that DUBs regulate antiviral immune response through targeting the TLR, RLR, and cGAS-STING signaling cascades, whether DUBs control IFI16 levels to mediate immune response against infection remains unknown." (PMID 37410794, 2023). "Studies have shown that under conditions of pathogen infection, the cGAS–STING pathway can induce autophagy without triggering type-I IFN or NF-κB signaling." (PMID 37686127, 2023). "It is possible that the low level of cGAMP produced by cGAS in cells that do not have the conjugation system is sufficient to protect against infection by P1, but not by T4, phage." (PMID 36848932, 2023). "Although the cGAS–STING pathway is inhibited during apoptosis, independent studies have confirmed that certain mechanisms ensure that moderate cGAS–STING-mediated type-I IFN production is triggered by mtDNA in response to pathogen infection." (PMID 37686127, 2023).
infection (continued). "We found that EV-A71 infection did not affect the expression of cGAS and STING in both HeLa and HT-29 cells." (PMID 36745686, 2023). "After infection of the body, HIV activates a series of nucleic acid receptors in cells, including RLRs, and AIM2-like receptors (AIM2 and IFI16), as well as the newly discovered cyclic GMP/AMP synthase (cGAS)." (PMID 35211115, 2022). "Chronic over-activation of cGAS-STING promotes inflammation that accelerates a variety of aging-related diseases, but inhibition of this pathway could increase vulnerability to infection." (PMID 35741054, 2022). "Our data on gene expression analysis in infected cGAS and TBK1 knockout cell lines identified a number of shared up- and down-regulated genes which collectively might contribute to establishment of infection resistance." (PMID 36405710, 2022). "Accumulating studies demonstrated that the cGAS-STING pathway, which is the vital cytosolic surveillance pathway (CSP), is essential for the induction of type I IFN response during the infection of a variety of intracellular bacterial pathogens (13, 19, 22, –, 31)." (PMID 35604097, 2022). "In cGAS knockdown cells, we observed that, although viral RNA levels were unchanged, there was a significant decrease in TNF and IL-6 mRNA transcript levels following infection." (PMID 35022513, 2022). "Notably, the explanation for the counterintuitive observation that RNA viruses stimulate DNA sensors cGAS/STING is, in part, through the release of mtDNA, which in turn can control the infection (77, –, 80)." (PMID 35073751, 2022). "In addition to interferon and proinflammatory cytokine production, autophagy activation is the important function of the cGAS–STING signaling pathway, which occurs after the infection of DNA viruses or DNA stimulation." (PMID 35458396, 2022). "Furthermore, cytosolic DNA sensor cyclic GMP-AMP synthase (cGAS) and immune adaptor protein stimulator of interferon genes (STING) were also required for the induction of type I IFN response during infection." (PMID 35604097, 2022). "We report here that HBx, as an HBV-specific component protein, downregulates the accumulation of cGAS expression by promoting its ubiquitination and autophagy, thereby escaping the innate immune response activated by the cGAS/STING signaling pathway and establishing an effective infection." (PMID 35346247, 2022). "During infection with d109, the virus enters the nucleus but fails to synthesize any nascent viral proteins or viral genomes; however, it robustly stimulates a cGAS-mediated innate immune response." (PMID 35110532, 2022). "However, upon initial activation, such as in the setting of infection, interferon produced by STING signaling increases cGAS expression as a means of signal amplification." (PMID 35693769, 2022). "In addition, Mabs-R, but not Mabs-S, strains enhanced inflammatory cytokines, in particular type I IFN production, through cGAS-STING-dependent pathways, to promote virulence during infection." (PMID 34447358, 2021). "In addition to inhibiting the cGAS/STING/TBK1 pathway, UL138 suppresses transcription from the viral major immediate early promoter that drives productive infection, and reduces the generation of infectious progeny virions during latency." (PMID 34903048, 2021). "The cGAS-STING-IRF3 signaling pathway is rapidly induced following HCMV lytic infection of endothelial and fibroblast cells, which is not only required for IFN-I induction but necessary to suppress viral replication." (PMID 34440891, 2021). "Given to the essential function of cGAS in sensing infection by DNA viruses, RNA viruses (such as HIV-1, dengue, Zika, CHIKV, and others, detailed below), and bacteria, these human pathogens evolve mechanisms to disable cGAS cytosolic DNA sensor function." (PMID 33927185, 2021).
infection (continued). "The present study evaluated the influence of ART on the expression of STING and cGAS, the production of type I IFN, and the levels of laboratory markers often used to monitor infection (CD4+, CD8+, and ratio of CD4+/CD8+ T cells and viral load) in a cohort infected with HIV-1." (PMID 33858455, 2021). "Despite this intricate mechanism of host–pathogen interaction, the cGAS–STING pathway is not relevant to alter in vivo infection outcomes." (PMID 35011636, 2021). "The cGAS-STING cascade is triggered upon cytosolic exposure of foreign nucleic acid species, following pathogen infection, but also by nucleus- and mitochondria-derived self-nucleic acids that leak into the cytosol following various types of stress and through DNA recombination processes." (PMID 33981307, 2021). "Although cyclic GMP-AMP synthase (cGAS)-stimulator of interferon genes (STING) signaling has been well recognized in defending DNA viruses, the role of cGAS-STING signaling in regulating infection of RNA viruses remains largely elusive." (PMID 34347572, 2021). "Mn2+ is a strong type I IFN stimulator that activates the cGAS-STING pathway in the absence of infection; thus, we reasoned that Mn would help to promote the activation of adaptive immune responses." (PMID 33767434, 2021). "Similarly, both cGAS and STING are required for INFβ production following infection of multiple cell types by Chlamydia trachomatis, a Gram-negative bacterium mainly causing disease of the genital tract." (PMID 33708225, 2021). "Overall, HPV evades cGAS/STING by its unique subcellular trafficking, a property that may contribute to establishment of infection." (PMID 33253291, 2020). "A dual-luciferase reporter assay in the absence of cGAS–STING showed that JSY13 infection increased the transcriptional activity of the IFN-β promoter, which was further enhanced by PRVΔUL13 mutants at 6 and 12 h post-infection." (PMID 32933581, 2020). "Conversely, ECTVΔvSlfn and ECTV-vSlfnΔp26 were completely impaired for such inhibition because infection with both mutant viruses showed notably high levels of STING, TBK1, and IRF3 phosphorylation and STING dimerization, indicative of activation of the cGAS-STING axis." (PMID 32948585, 2020). "Our findings suggest that PPP6C-mediated dephosphorylation of cGAS impairs its substrate binding activity and innate immune response, which is important to keep cGAS inactive in the absence of infection to avoid autoimmune responses." (PMID 32474700, 2020). "Similar to wildtype HPV infection, R302/5A mutant infection alone did not activate the cGAS/STING pathway." (PMID 33253291, 2020). "Later in the same year, it was reported by the Cui group that ZIKV can target cGAS for degradation via the enhanced stabilization of caspase-1 by nonstructural protein NS1 during infection." (PMID 32899347, 2020). "Immunoblotting of infected primary human fibroblasts revealed that endogenous cGAS is degraded as early as 4 hrs post infection and that this degradation is independent of global transcriptional or translational repression induced by CHIKV." (PMID 33057424, 2020). "Yet, the role of cGAS in protection against viruses that disseminate through the natural route of infection in natural hosts had not been studied." (PMID 31877196, 2019). "We demonstrate here that attenuated NH/P68, but not virulent Armenia/07, activates the cGAS-STING-IRF3 cascade very early during infection, inducing STING phosphorylation and trafficking through a mechanism involving cGAMP." (PMID 30918080, 2019). "In contrast, NH/P68 infection induces activation of the cGAS-STING route in the presence and absence of AraC, since phosphorylation of both STING and IRF3 are observed." (PMID 30918080, 2019). "We observed that DENV serotype 1, but not other serotypes, significantly upregulated cGAS mRNA expression 72 h post-infection in Tupaia cells." (PMID 31842286, 2019).